RAD21 (RAD21 cohesin complex component)
Description:
[Double-strand-break repair protein rad21 homolog]: As a member of the cohesin complex, involved in sister chromatid cohesion from the time of DNA replication in S phase to their segregation in mitosis, a function that is essential for proper chromosome segregation, post-replicative DNA repair, and the prevention of inappropriate recombination between repetitive regions. The cohesin complex may also play a role in spindle pole assembly during mitosis. In interphase, cohesins may function in the control of gene expression by binding to numerous sites within the genome (By similarity). May control RUNX1 gene expression (Probable). Binds to and represses APOB gene promoter. May play a role in embryonic gut development, possibly through the regulation of enteric neuron development (By similarity). [64-kDa C-terminal product]: May promote apoptosis.
Synonyms: hHR21; HR21; KIAA0078; NXP1; SCC1; CDLS4; HRAD21; MCD1; MGS
Tractability: Small molecule: a structure with a bound ligand is known. PROTAC: UniProt records ubiquitination sites on it; ubiquitination databases record sites on it; its protein half-life has been measured.
Gene: Protein-coding gene on chromosome 8 (116,845,934 to 116,874,849, reverse strand). Ensembl gene ENSG00000164754.
Subcellular location: Nucleus (Double-strand-break repair protein rad21 homolog); Nucleus matrix; Chromosome; Chromosome, centromere; Cytoplasm, cytoskeleton, spindle pole; Cytoplasm, cytosol (64-kDa C-terminal product); Nucleus
Subcellular location (Human Protein Atlas): Nucleoplasm
Pathways (Reactome):
Cell Cycle: Cohesin Loading onto Chromatin; Establishment of Sister Chromatid Cohesion; Resolution of Sister Chromatid Cohesion; Separation of Sister Chromatids
Metabolism of proteins: SUMOylation of DNA damage response and repair proteins
Reproduction: Meiotic synapsis
Signal Transduction: Estrogen-dependent gene expression
Gene Ontology:
Molecular function: protein binding; chromatin binding; cis-regulatory region sequence-specific DNA binding; DNA-binding transcription factor binding; lncRNA binding
Biological process: positive regulation of sister chromatid cohesion; protein localization to chromatin; regulation of transcription by RNA polymerase II; DNA recombination; double-strand break repair; establishment of meiotic sister chromatid cohesion; establishment of mitotic sister chromatid cohesion; reciprocal meiotic recombination; replication-born double-strand break repair via sister chromatid exchange; negative regulation of G2/M transition of mitotic cell cycle; negative regulation of gene expression; negative regulation of glial cell apoptotic process; negative regulation of interleukin-1 beta production; negative regulation of mitotic metaphase/anaphase transition; negative regulation of neuron apoptotic process; negative regulation of tumor necrosis factor production; positive regulation of gene expression; positive regulation of interleukin-10 production; response to hypoxia; sister chromatid cohesion
Cellular component: chromosome; cohesin complex; membrane; mitotic cohesin complex; nuclear matrix; nucleoplasm; nucleus; chromosome, centromeric region; cytosol; meiotic cohesin complex; chromatin; condensed nuclear chromosome; spindle pole
Genetic constraint (gnomAD): Loss-of-function variants: 12 observed, 57.08 expected, observed/expected ratio (o/e) 0.21, 90% interval 0.13 to 0.34. The upper end of that interval is the gene's LOEUF score, 0.34, which puts it in group 1 of 6, group 1 being the genes least tolerant of losing a copy. Missense variants: 457 observed, 726.72 expected, observed/expected ratio (o/e) 0.63, 90% interval 0.58 to 0.68. Synonymous variants: 232 observed, 241.76 expected, observed/expected ratio (o/e) 0.96, 90% interval 0.86 to 1.07.
Gene-disease validity (ClinGen):
ClinGen rates the evidence that RAD21 causes each of these diseases.
Cornelia de Lange syndrome (autosomal dominant): Definitive. A rare syndrome characterized by low birth weight, delayed growth, intellectual disabillity, behavioral problems, and a distinctive facial appearance (thin, arched eyebrows, low set ears, small teeth, and small nose).
Cancer hallmarks: invasion and metastasis (promotes); genome instability and mutations (suppresses); escaping programmed cell death (suppresses)
Homologues: Orthologues: chimpanzee RAD21 (100% identical), macaque RAD21 (99% identical), dog RAD21 (99% identical), pig RAD21 (98% identical), guinea pig RAD21 (98% identical), rabbit RAD21 (98% identical), rat Rad21 (97% identical), mouse Rad21 (97% identical), tropical clawed frog rad21 (83% identical), zebrafish rad21b (80% identical), zebrafish rad21a (77% identical), Drosophila melanogaster vtd (42% identical), and 1 more. Paralogues in human: RAD21L1 (42% identical), REC8 (19% identical).
Diseases named in the same sentence as RAD21 in open-access papers:
RAD21 is named in the same sentence as 145 diseases in open-access papers, as found by Europe PMC text mining. Sharing a sentence is not in itself a finding about the gene and the disease. The quoted sentences say what the papers report.
breast carcinoma (53 papers, 2007 to 2025). "RAD21 expression is associated with early recurrence and treatment resistance in sporadic breast cancer." (PMID 36077333, 2022). "Involved in the M-phase, RAD21 was overexpressed in carcinoma tissue; decreased levels of RAD21 have been reported to be associated with loss of cell proliferation in breast cancer." (PMID 29725503, 2018). "Enhanced RAD21 expression was associated with early relapse and poor prognosis of breast cancer and KRAS mutant colorectal cancer." (PMID 28977903, 2017). "Single nucleotide polymorphisms (SNPs) have been identified in RAD21 that predict susceptibility to breast cancer." (PMID 23145106, 2012). "In humans, patients with RAD21 mutations also have impaired DNA damage repair, and knock down of RAD21 sensitizes breast cancer cells to chemical agents that damage DNA." (PMID 22988450, 2012). "RAD21 is implicated in mediating estrogen-regulated transcription through ERα in MCF7 breast cancer cells." (PMID 22537934, 2012). "Our immunohistochemical analysis showed that RAD21 expression associates with shorter relapse-free survival in patients with high grade breast cancer." (PMID 21255398, 2011). "Further, an intronal single nucleotide polymorphism (SNP) in the RAD21 gene is strongly associated with increased breast cancer risk." (PMID 21255398, 2011). "Therefore, we explored the relationship between genome organization disorders associated with enhanced RAD21 expression and breast cancer oncogenesis and prognosis." (PMID 37381036, 2023). "Moreover, several studies have found that enhanced RAD21 transcription is correlated with increased gene copy number in breast cancer tissue, which is associated with poor prognosis and resistance to chemotherapy." (PMID 37381036, 2023). "Moreover, we combined transcriptome changes and chromatin structure alterations upon RAD21 up-regulation and revealed that the expression level of RAD21 is positively associated with breast cancer." (PMID 37381036, 2023). "Furthermore, RAD21 alterations were negatively associated with median overall survival in breast cancer." (PMID 35227290, 2022). "Interestingly, Rad21 has been shown to be co-localized with estrogen receptor α and associated with tumor progression in breast cancer cells." (PMID 28831167, 2017). "RAD21 encodes a key component of the cohesin complex, which is essential for chromosome segregation, and RAD21 deregulation may impact survival in breast cancer." (PMID 28915599, 2017). "In breast cancer, correlations have been identified between enhanced RAD21 expression (and the presence of specific nsSNPs) and overall breast cancer risks, and RAD21 over-expression is associated with poor prognosis and the acquisition of drug resistance." (PMID 23962039, 2013). "This joint high prevalence is consistent with MYC and RAD21 being closely linked on amplicon 8q24 and frequently coamplified in BRCA1-mutated breast cancer." (PMID 38869771, 2024). "To assess RAD21 aggregation in breast cancer cells with high RAD21 expression levels, we obtained three human breast cancer cell lines with high levels of RAD21 expression, and the MCF10A cell line was used as a reference." (PMID 37381036, 2023). "Compared with MCF10A cells, RAD21 was more aggregated and showed a high level of heterogeneity in the three selected breast cancer cell lines, indicating a tendency for the formation of vermicelli-like structures." (PMID 37381036, 2023). "It has been reported that increased RAD21 expression was positively correlated with the progression of multiple cancers, such as breast cancer, cervical cancer, and colon cancer." (PMID 35860572, 2022).
breast carcinoma (continued). "In our dataset, we found that among the top five disease ontologies in terms of RAD21 alteration prevalence, three were breast cancer histologies and one was prostate." (PMID 35227290, 2022). "Numerous studies have revealed that RAD21 is over expressed in a variety of tumors, such as colorectal cancer, non small cell lung cancer, and breast cancer." (PMID 36263204, 2022). "Expression studies have revealed a 2-fold increased expression of RAD21 in human breast cancer cell lines compared to normal breast tissue." (PMID 35205681, 2022). "It was demonstrated that RAD21 is overexpressed in 80% of breast cancer cell lines, in 30–40% of hormone-refractory prostate cancers and xenografts." (PMID 35227290, 2022). "Enhanced expression of cohesion and RAD21 is another prognostic factor associated with increased resistance to chemotherapy, mostly in HER2, basal, and luminal breast cancers." (PMID 35163783, 2022). "In breast cancer, RAD21 mRNA abundance was significantly higher in 8q23.3-amplified tumours compared to non-amplified tumours (FDR = 1.6 × 10− 7), indicating that RAD21 upregulation is driven in part by the genomic amplification." (PMID 33941236, 2021). "Knockdown of RAD21 in MDA-MB-231 breast cancer cells increased sensitivity to DNA-damaging agents cyclophosphamide, 5-fluorouracil and etoposide." (PMID 34202641, 2021). "Xu et al5 showed that the expression of Rad21 in breast cancer is related to the early recurrence of breast cancer." (PMID 29797792, 2018). "Mahmood et al8 also confirmed that Rad21 is one of the driver genes that regulate the proliferation/survival of clonogenic breast cancer cells presenting an amplification of the corresponding region." (PMID 29797792, 2018). "Several of these genes have been previously linked to tumourigenesis in breast cancer, including KDM5B, RAD21, BIRC5, AURKA and MSRA." (PMID 27341628, 2016). "High RAD21 expression was associated with genomic instability and miR-299-5p, a microRNA already involved in breast cancer and in oral squamous cell carcinoma, was predicted to be a RAD21 regulator." (PMID 24616890, 2014). "In our breast cancer cohort, RAD21 was found to be amplified in 36% of the tumor samples and to be highly associated with the cell cycle trait." (PMID 23382830, 2013). "Correlation of RAD21 expression with breast cancer-specific survival was further assessed for BRCA1, BRCA2, and BRCAX cancers." (PMID 22537934, 2012). "Gene-expression profiling of 31 breast cancer patients with supraclavicular lymph node metastasis revealed RAD21 as one of six genes that were differentially expressed between good- and poor-outcome groups." (PMID 22537934, 2012). "We performed an immunohistochemical analysis of RAD21 expression in a cohort of 94 familial breast cancers (28 BRCA1, 27 BRCA2, and 39 BRCAX) and correlated these data with genotype and clinicopathologic parameters, including survival." (PMID 22537934, 2012). "Our previous study on sporadic breast cancers showed that RAD21 overexpression correlated with early relapse in high-grade breast cancers regardless of intrinsic tumor subtype." (PMID 22537934, 2012). "As for sporadic breast cancers, RAD21 expression correlated with shorter survival in grade 3 (P = 0.009) and but not in grade 1 (P = 0.065) or 2 cancers (P = 0.090)." (PMID 22537934, 2012). "A significant correlation was noted between high-RAD21 expression and shorter relapse-free survival (P = 0.038) and breast cancer-specific survival (P = 0.001) across the entire familial cancer group." (PMID 22537934, 2012). "RAD21 is thus a potential BRCA1/2 mutation status-dependent predictive and prognostic marker in familial breast cancers." (PMID 22537934, 2012). "In keeping with our previous findings in sporadic breast cancers, RAD21 gene expression correlated with copy number in our cohort of familial breast cancers." (PMID 22537934, 2012).
breast carcinoma (continued). "Silencing of RAD21 gene expression decreased cell growth and enhanced cytotoxicity of etoposide and bleomycin in human breast cancer cells." (PMID 22905093, 2012). "Nevertheless, although mir-299-5p is clearly reduced in breast cancer, this appears appear to play a relatively minor role in regulating RAD21 expression (r2 = 0.0864; P = 0.002) compared with genomic changes in copy number (r2 = 0.286; P < 0.001)." (PMID 22537934, 2012). "Similar to our earlier findings in sporadic breast cancers, increased RAD21 expression in BRCA2 and BRCAX cancers confers a poor prognosis and resistance to DNA-damaging chemotherapeutic agents." (PMID 22537934, 2012). "When the intrinsic subtypes were individually analyzed, high RAD21 expression correlated with worse survival in luminal breast cancers (P = 0.010)." (PMID 22537934, 2012). "We, and others, also showed that RAD21 knockdown confers in vitro resistance to DNA-damaging chemotherapeutic agents, which recapitulated the findings in our cohort of sporadic breast cancers." (PMID 22537934, 2012). "We therefore performed an immunohistochemical analysis of RAD21 expression in a cohort of familial breast cancers." (PMID 22537934, 2012). "RAD21 expression is a prognostic and predictive factor that affects the ultimate outcome in many breast cancer sub-histotypes." (PMID 21255398, 2011). "The decrease in cell survival that correlated with levels of RAD21 in breast cancer cells after RAD21 knockdown, is, therefore, in keeping with the dependence of breast cancer cells on the HR pathway to repair DNA damage from chemotherapy." (PMID 21255398, 2011). "Our analyses provide compelling evidence that RAD21 expression is a novel prognostic marker in breast cancer and is also highly predictive of anti-cancer therapy outcomes." (PMID 21255398, 2011). "This translational study is the first comprehensive analysis of a novel chromosomal DNA repair protein, RAD21 cohesin, in breast cancer." (PMID 21255398, 2011). "Chemosensitivity was assessed in breast cancer cell lines with an engineered spectrum of RAD21 expression." (PMID 21255398, 2011). "Variations in RAD21 mRNA expression in the clinical samples were reflected in the gene expression data from 36 breast cancer cell lines." (PMID 21255398, 2011). "Knockdown of RAD21 in the MDA-MB-231 breast cancer cell line significantly enhanced sensitivity to cyclophosphamide, 5-fluorouracil and etoposide." (PMID 21255398, 2011). "RAD21 alterations are relatively common according to TCGA PanCancer atlas studies (7% of all queried patients), which show elevated RAD21 in 20% of ovarian cancer cases and 13% of breast cancer cases." (PMID 37381036, 2023). "In addition, the RAD21 expression levels in the breast cancer tissues of patients with four cancer subtypes were significantly higher than those measured in normal tissues." (PMID 37381036, 2023). "Another study proposed that RAD21 could be a target for breast cancer drugs, because RAD21-targeted siRNA increased the sensitivity of cells to two chemotherapeutic drugs." (PMID 37381036, 2023). "Importantly, we find that in breast cancer cells, the expression of RAD21 is aberrantly high with poor patient survival and RAD21 forms beads in the nucleus." (PMID 37381036, 2023). "In addition, to obtain insight into the relationship between up-regulated RAD21 and breast cancer, we subjected the differentially expressed genes in RAD21-OE cells versus control to gene set enrichment analysis (GSEA)." (PMID 37381036, 2023). "Variation in the Rad21 gene is probably involved in hereditary breast cancer development." (PMID 35163783, 2022).